CHD8 (chromodomain helicase DNA binding protein 8)
Diseases named in the same sentence as CHD8 in open-access papers (continued):
Sharing a sentence is not in itself a finding about the gene and the disease.
Kabuki syndrome (3 papers, 2020 to 2025). Kabuki syndrome (KS) is a multiple congenital anomaly syndrome characterized by typical facial features, skeletal anomalies, mild to moderate intellectual disability and postnatal growth deficiency. "Along with the chromatin regulators PHC1 (microcephaly) and KDM6A (Kabuki syndrome), another paradigmatic example is the ATP-dependent chromatin remodeler CHD8 (mSNC in enhancer), which controls neural progenitor cell proliferation through WNT-signaling related genes." (PMID 32299352, 2020).
microcephaly (3 papers, 2020 to 2025). A congenital or acquired developmental disorder in which the circumference of the head is smaller than normal for the person's age and sex. "The case of CHD8-associated microcephaly highlights the potential influence of genetic modifiers or additional pathogenic mechanisms." (PMID 40019509, 2025). "Conversely, three cases with pathogenic variants in CHD8, WAC, and MED12 exhibited microcephaly, despite these genes typically not being associated with reduced head size." (PMID 40019509, 2025).
acute lymphoblastic B-cell leukemia (2 papers, 2015 to 2020). "CHD8 is required for survival of pre-B cells, acute lymphoblastic B-cell leukemia cells, and EμMyc B-cell lymphomas." (PMID 32453735, 2020). "We identified the chromatin-modifying protein CHD8 as necessary for cell survival in a mouse model of BCR-Abl+ B-cell acute lymphoblastic leukemia." (PMID 26588464, 2015). "Of the CHD subfamily III, CHD7 regulates developmental hematopoiesis and expansion of hematopoietic stem and progenitor cells, whereas CHD8 is required for survival of both non-transformed pre-B cells and acute lymphoblastic B-cell leukemia cells as well as EμMyc B-cell lymphomas." (PMID 32453735, 2020).
bipolar disorder (2 papers, 2017 to 2021). A disorder of the brain that causes unusual shifts in mood, energy, activity levels and the ability to carry out day-to-day tasks. "Previous studies have shown that CHD8 protein negatively regulates Wnt signaling by interacting with β-catenin: Wnt/β-catenin signaling plays a critical role in normal brain development and has been implicated in bipolar disorder (BD), SZ, ASD, and cancer." (PMID 28321286, 2017).
fragile X syndrome (2 papers, 2021 to 2025). A genetic syndrome caused by mutations in the FMR1 gene which is responsible for the expression of the fragile X mental retardation 1 protein. "Defects with a large effect seen in syndromes such as the PMDS or fragile X syndrome, but also mutations affecting high confidence ASD risk genes such as SCN2A and CHD8 will represent primary targets of such new therapies." (PMID 34784886, 2021).
leukemia (2 papers, 2020 to 2025). A malignant (clonal) hematologic disorder, involving hematopoietic stem cells and characterized by the presence of primitive or atypical myeloid or lymphoid cells in the bone marrow and the blood. "In leukemia cells, NSD3S has been shown to be essential for cancer progression by bridging the interaction between the bromodomain containing protein 4 (BRD4) and chromodomain helicase DNA binding protein 8 (CHD8)." (PMID 31638140, 2020).
lymphoma (2 papers, 2015 to 2018). A malignant (clonal) proliferation of B- lymphocytes or T- lymphocytes which involves the lymph nodes, bone marrow and/or extranodal sites. "KP lymphoma cells deplete upon CHD8 knockdown in growth competition assays, but to a lesser extent than B cell malignancies." (PMID 26588464, 2015).
22q11.2 deletion syndrome (1 paper, 2019). 22q11.2 deletion syndrome (DS) is a chromosomal anomaly which causes a congenital malformation disorder whose common features include cardiac defects, palatal anomalies, facial dysmorphism, developmental delay and immune deficiency. "Interestingly, the single gene, CLTCL1, found to be similarly hypomethylated in both the 16p11.2del and CHD8+/− signatures, is found in the 22q11.2 deletion syndrome (22qDS; OMIM# 611867) deletion region." (PMID 31311581, 2019).
acute lymphoblastic leukemia (1 paper, 2016). Leukemia with an acute onset, characterized by the presence of lymphoblasts in the bone marrow and the peripheral blood. "For the interaction partner of FAM124B, CHD8, one study so far described an oncogenic role in a mouse model for BCR-ABL1+ acute lymphoblastic leukemia, while neither the role of FAM124B nor its interaction with CHD7/8 have been described so far in AML." (PMID 27585840, 2016).
acute myeloid leukemia (1 paper, 2021). Acute myeloid leukemia (AML) is a group of neoplasms arising from precursor cells committed to the myeloid cell-line differentiation. "In line with the function of NSD3-short as an adaptor protein of BRD4 and CHD8, MLL-AF9 rearranged acute myeloid leukemia (AML) were proven to be dependent on NSD3." (PMID 34440470, 2021).
asthma (1 paper, 2023). "These four genes, SMARCC1, SETD2, KMT2B, and CHD8, were used to construct a nomogram model for predicting the prognosis of patients with severe asthma." (PMID 37245015, 2023). "The nomogram constructed using the four CRs, SMARCC1, SETD2, KMT2B, and CHD8, may be a useful tool for predicting the prognosis of patients with severe asthma." (PMID 37245015, 2023).
Burkitt lymphoma (1 paper, 2015). A rare form of malignant mature B-cell non-Hodgkin lymphoma. "To determine whether dependency on CHD8 extends to other hematopoietic malignancies, we first tested another cancer of the B cell lineage, a murine model of Burkitt’s lymphoma." (PMID 26588464, 2015).
colitis (1 paper, 2023). Inflammation of the colon. "Although further research is needed to determine whether chd8 is necessary for the establishment and/or the maintenance of the mucosal barrier, we speculate that patients with chd8 mutations are more prone to bacterial infection and/or colitis because of the altered mucosal barrier." (PMID 36375841, 2023).
Constipation (1 paper, 2021). Infrequent or difficult evacuation of feces. "Furthermore, a study showed that individuals with ASD that exhibit mutations in the chromodomain helicase DNA binding protein 8 (CHD8) gene were reported to have constipation." (PMID 33450950, 2021).
Dystonia (1 paper, 2024). An abnormally increased muscular tone that causes fixed abnormal postures. "We describe three additional unrelated female individuals, each carrying a different CHD8 frameshift variant and whose clinical presentations were primarily characterized by young-onset dystonia." (PMID 38441608, 2024). "In 2021, our group described two singular female patients with CHD8-related neurodevelopmental disorder and striking dystonic manifestations, prompting the suggestion that dystonia should be considered a possible component of this condition." (PMID 38441608, 2024). "This work validates our previous observation that dystonia is part of the phenotypic spectrum of CHD8-related neurodevelopmental disorders with potential female preponderance, raising new challenges and opportunities in the diagnosis and management of this condition." (PMID 38441608, 2024).
hearing loss (1 paper, 2025). "Reanalysis through genome sequencing aimed to clarify the inheritance of the CHD8 variant, identify alternative causative variants, and investigate a genetic basis for her familial hearing loss." (PMID 41407309, 2025). "In contrast, our proband's hearing loss is likely not to be related to the CHD8 variant, given the distinct maternal family history and its segregation pattern, suggesting a distinct genetic etiology." (PMID 41407309, 2025).
Hirschsprung disease (1 paper, 2023). Hirschsprung disease (HSCR) is a congenital intestinal motility disorder that is characterized by signs of intestinal obstruction due to the presence of an aganglionic segment of variable extent in the terminal part of the colon. "Contrary to Hirschsprung’s disease (HSCR; MIM#142623), a congenital condition associated with a failure of vagal NCCs to colonize the intestine, we found that the reduced expression of chd8 does not prevent the completion of the rostro-caudal colonization of the GI tract by vagal NCCs." (PMID 36375841, 2023).
Infertility (1 paper, 2024). "Adult mice with germline-specific Chd8 deletion displayed apparent atrophy of testes and infertility." (PMID 38224953, 2024). "We observed that Chd8 ablation in germ cells leads to testicular atrophy and infertility." (PMID 38224953, 2024).
Lissencephaly (1 paper, 2021). A spectrum of malformations of cortical development caused by insufficient neuronal migration that subsumes the terms agyria, pachygyria and subcortical band heterotopia. "Previously, neuronal migration defects have also been observed in organoids derived from patients with lissencephaly, periventricular heterotopia, and in CHD8 deficient mice." (PMID 34433918, 2021).
liver cancer (1 paper, 2022). An epithelial or non-epithelial malignant neoplasm that arises from the liver. "Nonetheless, human patients with a lower expression of CHD8 have a favorable prognosis in liver cancer." (PMID 37354463, 2022).
Neurodevelopmental delay (1 paper, 2017). "CHD8 het mice had neurodevelopmental delay as identified using mouse brain gene set enrichment analysis and suppression of many neuronal genes via the RE-1 silencing transcription (REST) factor." (PMID 28680792, 2017).
neuropathies (1 paper, 2021). "Based on the affected cell type, these disorders can be divided into three subtypes: neuropathies (neuronal defects) that seem to hold true for CHD8/chd8, Slc6a4 and Nlgn3, myopathies (smooth muscle cell defects), or mesenchymopathies (ICC defects as seen for Nos1)." (PMID 32461615, 2021).
psychosis (1 paper, 2019). "There has been recent evidence on rare variants in the gene being implicated in psychosis, which adds to the notion of the cross-disorder nature of CHD8 pathways." (PMID 31078131, 2019).
ptosis (1 paper, 2025). The drooping of the upper eyelid. "We conducted genome sequencing through the Undiagnosed Diseases Network (UDN) in a female proband harboring a CHD8 variant of uncertain significance (VUS), whose clinical presentation was consistent with IDDAM but included atypical features such as ptosis and hearing loss." (PMID 41407309, 2025).
rectum carcinoma (1 paper, 2020). "We previously noted the link to cancer for CHD8 haploinsufficiency, highlighting that the father of a patient with a paternally inherited CHD8 sequence mutation, who also had similar autistic features to the patient, developed cT2N1 rectum carcinoma." (PMID 33282601, 2020).
scoliosis (1 paper, 2022). A congenital or acquired spinal deformity characterized by lateral curvature of the spine. "While the combination of behavioural issues with scoliosis is quite striking and corresponds with the phenotype of the individuals with pathogenic and likely pathogenic variants in CHD8, the phenotype is not specific enough to warrant a definitive conclusion on the variant’s pathogenicity." (PMID 36182950, 2022).
skin ulceration (1 paper, 2025). "Chd8−/− mice were small, lacked mobility, lost hair, developed skin ulceration, and deceased in 5–7 weeks after birth (data not shown)." (PMID 40155813, 2025).
Sleep disturbance (1 paper, 2025). An abnormal pattern in the quality, quantity, or characteristics of sleep. "Approximately 67% of individuals with CHD8 mutations report severe sleep disturbances." (PMID 41425200, 2025).
Snijders Blok-Campeau syndrome (1 paper, 2023). Snijders Blok-Campeau syndrome (SNIBCPS) is an autosomal dominant neurodevelopmental disorder characterized by global developmental delay with impaired intellectual development and delayed speech acquisition. "Pathogenic variants in CHD proteins contribute to the development of a range of neurological disorders, such as CHD1 in Pilarowski-Bjornsson syndrome, CHD3 in Snijders Blok-Campeau syndrome (SNIBCPS), CHD4 in Sifram-Hitz-Weiss syndrome, CHD7 and CHD8 in Autism Spectrum Disorder (ASD)." (PMID 36647159, 2023).
T-cell lymphoma (1 paper, 2015). "We also examined CHD8 dependency in a spontaneous T-cell lymphoma cell line derived from a K-rasLA2/+; p53LSL/LSL mouse (hereafter referred to as KP)." (PMID 26588464, 2015). "T-ALL cells expressing the intracellular domain of Notch (ICN) were less dependent on CHD8 expression, and ectopic expression of ICN in K-ras driven T-cell lymphoma cells partially rescued the dependency of these cells on CHD8 expression." (PMID 26588464, 2015).
Testicular atrophy (1 paper, 2024). Wasting (atrophy) of the testicle (the male gonad) manifested by a decrease in size and potentially by a loss of fertility. "After treatment of 8-week-old male mice with tamoxifen, acquired deletion of Chd8 in germ cells (Ddx4-CreERT2; Chd8F/F) resulted in gradual testicular atrophy and a defect in sperm production." (PMID 38224953, 2024).
triple-negative breast carcinoma (1 paper, 2025). An invasive breast carcinoma which is negative for expression of estrogen receptor (ER), progesterone receptor (PR), and human epidermal growth factor receptor 2 (HER2). "This study uses multi-omics and biophysical analyses to identify chromatin remodeler CHD8 as a triple negative breast cancer (TNBC)-specific, targetable interaction partner of oncogene BCL11A." (PMID 40328966, 2025).
cancer (28 papers, 2010 to 2025). A tumor composed of atypical neoplastic, often pleomorphic cells that invade other tissues. "Several known cancer-associated genes are located on 14q, including CHD8, FOXA1, HIF1A, and DICER1, encoding proteins involved in DNA damage/response, hypoxia response, and miRNA processing, respectively." (PMID 34205964, 2021). "Here, our findings of key DEGs that have wide-ranging involvement in both neurodevelopment and cancer further serve to underline the importance of cancer screening for patients with CHD8 haploinsufficiency." (PMID 33282601, 2020). "Disruption of CHD8 is also implicated in cancer, as is the disruption of the destruction complex of beta-catenin." (PMID 31335867, 2019). "The mechanisms by which loss of function CHD8 mutations increase cancer risk are likely to be multifactorial." (PMID 28321286, 2017). "Loss of CHD8 function has been observed in a broad range of tumor types and other chromatin regulators have been implicated in cancer development." (PMID 26733790, 2015). "In addition, a number of studies reported frequent mutations in human cancers: CHD6 in bladder cancer, CHD7 in medulloblastoma, whereas CHD8 harbors mutations in many cancer types." (PMID 32453735, 2020). "NSD3 drives progression of multiple cancers, mainly through the NSD3–BRD4–Chromodomain-helicase-DNA-binding protein 8(CHD8) axis and the BRD4–NSD3–MYC axis, and is closely associated with poor overall survival and progression-free survival of cancer patients." (PMID 36770884, 2023). "For instance, we identified phase shifted transcript pairs from different cancer hallmark genes such as BIRC5 in HCT116_WT, PCGF2 in HCT116_ARNTLKO, ABCA2 in HCT116_NR1D1KO, and CHD8 in HCT116_PER2KO." (PMID 35552415, 2022). "There was significant overlap; 8/14 genes involved in OGID were somatically mutated in a diverse range of cancers (NSD1, EZH2, DNMT3A, PTEN, CHD8, HIST1H1E, MTOR, PIK3CA; p = 1.7 × 10−14)." (PMID 28475857, 2017). "One of the most interesting characteristics of CHD8 is its diverse effect on several neuropsychiatric and neurodevelopmental disorders and cancer." (PMID 28321286, 2017). "No other disease gene sets from the 184 lists for complex disease and traits available from the National Human Genome Research Institute were as significantly enriched as the ASD or cancer gene sets for CHD8 targets or genes affected by CHD8 knockdown." (PMID 26733790, 2015). "Previously, it had been observed that CHD8 is overexpressed in murine cancer cell lines compared to corresponding normal tissues." (PMID 26588464, 2015). "We believe that these results support investigating a possible role for CHD8 inhibitors as anti-cancer drugs." (PMID 24265227, 2014). "These seemingly contradictory results probably reflect context-dependent transcriptional regulation by CHD8, a feature particularly apparent in cancer, where CHD8 has been proposed to operate as a tumor suppressor in some malignancies and a proto-oncogene in others." (PMID 36222238, 2022). "This suggests CHD8 may have other important roles extending past development and may be a point of commonality between some cancers and ASD." (PMID 26733790, 2015). "CHD8 bound genes were also highly enriched in TGCA cancer associated genes and also showed no specific enrichment in either up or downregulated genes." (PMID 26733790, 2015). "Thus, the finding that CHD8 binds to β-catenin, inhibiting its transcriptional effects, is relevant to the role of CHD8 in both neuropsychiatric and neurodevelopmental disorders, as well as cancers." (PMID 28321286, 2017).
cancer (continued). "Over the past several years, NSD3S has been established as an adaptor protein for important drivers of cancer, such as MYC, BRD4, and CHD8." (PMID 38256018, 2024). "Our work thus identifies MAPK signaling as a potential therapeutic target for the treatment of the CHD8 ASD subtype and suggests that cancer drugs targeting the MAPK pathway may be therapeutically active in idiopathic autism." (PMID 36222238, 2022). "As growth factors-independent proliferation is a hallmark of many types of tumours, it will be interesting to investigate whether the presence of CHD8 in the absence of serum at G1/S promoters is a general characteristic of cancer cells." (PMID 24265227, 2014).